CCND2 (cyclin D2)
Diseases named in the same sentence as CCND2 in open-access papers (continued):
Sharing a sentence is not in itself a finding about the gene and the disease.
keloid (1 paper, 2025). An irregularly shaped, elevated mark on the skin caused by deposits of excessive amounts of collagen during wound healing. "The findings reveal a significant positive correlation between high expression of CCND2 and keloid formation, identifying CCND2 as a risk factor for keloids." (PMID 40487928, 2025). "The forest plot for CCND2 shows that the combined effect sizes of SNPs associated with this gene are consistently >0, confirming its role as a high-risk gene for keloid development." (PMID 40487928, 2025). "Specifically, CCND2 is recognized as a risk factor for keloid, while KLF4 functions as a protective factor against keloid formation." (PMID 40487928, 2025). "Specifically, CCND2 was associated with keloids with an IVW OR of 1.410 (95% CI: 1.001–1.985, P = .049), suggesting a potential causal relationship." (PMID 40487928, 2025). "Based on MR analysis, CCND2 positively correlated with keloid risk [IVW OR: 1.410; 95% confidence interval (CI): 1.001–1.985, P = .049]." (PMID 40487928, 2025). "In the scatter plot for CCND2, all five lines have slopes >0, confirming that CCND2 is a high-risk gene for keloid development." (PMID 40487928, 2025). "For CCND2, the beta coefficient was positive, and the OR exceeded 1, suggesting that higher expression levels of CCND2 are associated with an increased risk of keloid formation." (PMID 40487928, 2025). "Bioinformatics and Mendelian randomization analyses identified two intersecting genes, CCND2 and KLF4, as core genes associated with keloid." (PMID 40487928, 2025). "In summary, CCND2 emerges as a pivotal factor in keloid development, acting through its multifaceted effects on cell cycle regulation, proliferation, and cytokine signaling." (PMID 40487928, 2025). "Further research into the precise mechanisms by which CCND2 influences keloid formation could provide valuable insights for the development of targeted therapies." (PMID 40487928, 2025). "The MR results for the two core genes (CCND2 and KLF4) in relation to keloid were evaluated for heterogeneity using Cochran’s Q statistic, with additional tests performed using the MR Egger and IVW methods." (PMID 40487928, 2025). "Consequently, CCND2 and KLF4 were identified as core genes in our study, providing valuable insights into the pathogenesis of keloids and highlighting potential targets for therapeutic intervention." (PMID 40487928, 2025). "This study not only highlights the pivotal roles of CCND2 and KLF4 in the development of keloids but also provides novel molecular targets and a theoretical foundation for the prevention and treatment of keloids." (PMID 40487928, 2025).
kidney cancer (1 paper, 2025). Primary or metastatic malignant neoplasm involving the kidney. "The cell-intrinsic antiproliferative effects of HIF2 inhibitors in kidney cancer are caused by loss of cyclin D1 activity, and upregulation of cyclin D2 or D3 are potential resistance mechanisms." (PMID 40178040, 2025).
left ventricular hypertrophy (1 paper, 2019). Enlargement of the LEFT VENTRICLE of the heart. "This could be explained by TRx action inhibiting cyclin D2 gene whose function is associated with left ventricular hypertrophy." (PMID 31513640, 2019).
lipodystrophy (1 paper, 2018). A congenital or acquired disorder characterized by abnormal loss or redistribution of the adipose tissue in the body. "Published functional data support such pleiotropy; for example, the gene product of CCND2 is thought to be involved in pancreatic beta cell growth (in line with the Proinsulin cluster) and also in early stage adipocyte differentiation (consistent with the Lipodystrophy cluster)." (PMID 30240442, 2018).
liver fibrosis (1 paper, 2023). "We performed real-time PCR for Tgfβ1, Tnfα, Colα1, Pdfgrs, Timp-1, CCND2, and Mycn, the key factors for NASH, liver fibrosis, and liver tumor in WT, the dKO, and the tKO mouse livers." (PMID 37586586, 2023).
malignant glioma (1 paper, 2018). A grade III or grade IV glioma arising from the central nervous system. "Mutations or amplifications of CCND2 genes were found in patients with malignant gliomas or hematologic malignancies." (PMID 30308939, 2018).
mental disorder (1 paper, 2024). A disease that has its basis in the disruption of mental process. "Besides, CCND2 has been found to be associated with central nervous system diseases and mental disorders." (PMID 38183038, 2024).
metastatic melanoma (1 paper, 2011). A melanoma that has spread from its primary site to another anatomic site. "Although some of these genes (e.g. cell cycle genes CCND2, CCNE1 and PCNA) had fold changes that were in a different direction when compared to metastatic melanoma patients, this is likely to be due to the active growth of these cells in culture." (PMID 21615965, 2011).
microphthalmia (1 paper, 2016). Congenital or developmental anomaly in which the eyeballs are abnormally small. "Unlike the microphthalmia seen in the cyclin D1–null mouse, no gross retinal phenotype has been identified in the cyclin D2–null mouse." (PMID 27957530, 2016).
Myocardial fibrosis (1 paper, 2021). "Specifically, inhibition of ZFAS1 could potentially alleviate myocardial fibrosis in DbCM by inhibiting cardiomyocyte ferroptosis by sponging miR‐150‐5p to activate CCND2." (PMID 34609043, 2021).
myoepithelial carcinoma (1 paper, 2025). "CCND2 overexpression has not been described previously in myoepithelial carcinoma and we found only one reference to immunohistochemical expression of CDK4 in this disease." (PMID 40379813, 2025).
myxofibrosarcoma (1 paper, 2021). A malignant fibroblastic neoplasm arising from the soft tissue. "A highly variable number of DMRs were identified in Myxofibrosarcomas, which were not shared across the sets and included the following genes: MEST (chr 7), C14MC microRNA cluster (also known as miR-379–656; chr 14), SNRPG and FAM136A (both in chr 2) and CCND2 (chr 12)." (PMID 33436720, 2021).
non-Hodgkin B cell lymphomas (1 paper, 2014). "A pool of important genes involved in B-cell development, oncogenesis, cell cycle regulation, and cell death including BATF, LIMD1, CFLAR, PIM2, and CCND2 are common signatures associated with IRF4 in non-Hodgkin B cell lymphomas." (PMID 25207815, 2014).
oral cancers (1 paper, 2019). "The inhibition of miR-155 under melatonin administration was significant, as miR-155 is known to modulate additional pathways of cellular proliferation and apoptosis in oral cancers through p27Kip1 and BCL6/cyclin D2." (PMID 31052365, 2019).
periodontitis (1 paper, 2015). An acute or chronic inflammatory process that affects the tissues that surround and support the teeth. "CD24, EST1, MTSS1, ING3, CCND2 and SYNE2 may have the potential to be used as targets for periodontitis diagnosis and treatment.; however, more research is still needed to validate our findings." (PMID 26705104, 2015). "EST1, MTSS1, ING3, CCND2 and SYNE2, as well as their corresponding miRNAs, might be potential therapeutic targets for periodontitis." (PMID 26705104, 2015).
plasma cell tumors (1 paper, 2012). "The NF-κB2 mutant p80HT promotes the development of plasma cell tumors by transcriptional activation of genes critical for the generation, proliferation and survival of plasma cells, including cyclin D1, cyclin D2, Blimp1, survivin, IL-10 and IL-15." (PMID 22642622, 2012).
prostatic adenocarcinoma (1 paper, 2020). "miR-615-5p expression was also markedly lower than normal cells and tissue in prostatic adenocarcinoma, in which CCND2 mRNA (cyclin D2) was upregulated in the absence of the inhibitory effect of miR-615-5p, promoting cell cycle progression." (PMID 32605009, 2020).
psoriasis (1 paper, 2021). An autoimmune condition characterized by red, well-delineated plaques with silvery scales that are usually on the extensor surfaces and scalp. "Increased levels of Keap1–G1/S-specific cyclin D2 adducts were also observed in psoriasis, but their role in the regulation of apoptosis and the onset of psoriasis is not certain." (PMID 34576119, 2021).
serous ovarian cancer (1 paper, 2015). "The most frequently hypermethylated genes in stromal progenitor cells from ascites and corresponding bulk tumor tissues from the patients with serous ovarian cancer at an advanced stage were CDKN2B, RASSFIA, DLC1, and CCND2." (PMID 26597084, 2015).
Stroke (1 paper, 2015). Sudden impairment of blood flow to a part of the brain due to occlusion or rupture of an artery to the brain.
testicular embryonal carcinoma (1 paper, 2024). A malignant germ cell neoplasm arising from the testis. "Activation of ESR1 increases CCND2 expression and induces proliferation of human testicular embryonal carcinoma NT2/D1 cells." (PMID 39342193, 2024).
testicular tumors (1 paper, 2019). "High level expression of CCND2 gene was observed in ovarian and testicular tumors." (PMID 31721901, 2019).
tumor (273 papers, 2003 to 2026). "In tumors, variant 3 targets genes such as CyclinD2 (CCND2) and drives aberrant tumor cell proliferation." (PMID 40723888, 2025). "ROC analysis and survival analysis results showed that high expression of CCND2 was associated with longer overall survival and progression-free survival, further emphasizing its importance in tumor prognosis assessment." (PMID 40678058, 2025). "Dysregulation of this process through CCND2 alteration can cause tumor proliferation and cell growth." (PMID 40009379, 2025). "The results suggest that the increased cyclin D2 expression by L1 is required to induce proliferative, motile tumor development in CRC tissue and can serve as a diagnostic marker and a target for CRC therapy." (PMID 39513917, 2024). "The search for the upregulated genes in three types of CSCs revealed Actn3, Ccnd2, Col4a1, and Col4a2, which have been linked to tumor aggressiveness, poor prognosis, cancer cell proliferation, and cell migration." (PMID 35063003, 2022). "The investigators also found a decrease in cyclin D2 promoter methylation and consequently an increase in cyclin D2, associated with the prevention of tumor progression." (PMID 34638282, 2021). "Tissue microarray and RNAscope in situ hybridization were used to detect CCND2 mRNA expression in 117 ABC-DLBCL tumor tissues and associations between CCND2 expression and progression-free survival was analyzed." (PMID 32850340, 2020). "For example, the methylation for CpG site CCND2 in Tumor 7 was 0.43, which means that 43% of the CCND2 alleles in the tumor fraction were methylated and 57% were not." (PMID 30953488, 2019). "In our study, we found lower all-cause mortality among women with promoter methylation (or loss of CCND2 expression) in tumor tissue." (PMID 28222775, 2017). "In cancers, cyclin D2 has been associated with tumor enhancer and suppressor functions." (PMID 40723239, 2025). "Finally, we verified the association between key NKRGs, KLRB1 and CCND2, and tumor-infiltrating NK cells by combining spatial transcriptomics and IHC assays based on BRCA tissue specimens." (PMID 39507529, 2024). "KLF-4 is a transcription factor with anti-proliferative effects in differentiated cells; in PC malignancies it acts as a tumor suppressor by upregulating p21CIP and downregulating c-Myc and cyclin D2 and is also associated with melphalan and carfilzomib drug resistance." (PMID 36752202, 2023). "Moreover, an increase in cyclin D2 is associated with tumor-suppressing behavior, inhibiting tumor cell growth and leading to apoptosis." (PMID 37568789, 2023). "As an example, it has been demonstrated that endothelial cell-derived exosomal miR-503, which is increased after neoadjuvant chemotherapy, can impair tumor growth, invasion, and proliferation in BC by inhibiting the expression of cyclin D2- and D3-encoding genes (CCND2 and CCND3)." (PMID 37153758, 2023). "As cell cycle arrest causes apoptosis in many tumor types, targeting CCND2 expression may contribute to the cytotoxic effects of R-CHOP." (PMID 32850340, 2020). "Moreover, the protein and mRNA levels of Pbk, Mcm2, Cyclin B2, Cyclin D2 and Cyclin A were markedly increased in menin-deficient tumours and dramatically rescued to normal levels by β-catenin ablation in mice." (PMID 25517963, 2014). "Additionally, the downregulation of oncogenes and cancer-associated genes, such as IL6, MMP2, and CCND2, may deprive the tumor cell of its growth advantage." (PMID 40043049, 2025). "Studies with the ApcMin/+ transgenic mouse model for CRC development showed that cyclin D2 is upregulated immediately after Apc loss in cells with deregulated Wnt/β-catenin signaling and that cyclin D2 deficiency reduces the proliferation and tumor burden after Apc loss." (PMID 39513917, 2024).
tumor (continued). "Examination of D-type cyclin protein overexpression in relation to the TNM stage of the tumours revealed that overexpression of cyclins D1 and/or D2, but not cyclin D3, is linked to colon carcinogenesis and that overexpression of cyclin D2 may be related to a higher TNM stage of the tumour." (PMID 16012517, 2005). "In our exploration of the core genes CCND2 and KLF4, we identified associations between their expression and the development of specific tumor types." (PMID 40487928, 2025). "Glycolysis genes HK1, GAPDH, ENO1, LDHA, and PKM, and cell cycle genes (except CCND2) were among the most tumor-specific genes." (PMID 39774001, 2025). "Using survival package, univariate correlation analysis showed that 8 characteristics, stage III, IV, serous type, mixed type, G2 grade, G3 grade, tumor invasion (≥ 50%), and high CCND2 expression were significantly correlated with overall survival (OS)." (PMID 40678058, 2025). "This increase in tumor size and weight required the induction of cyclin D2 by L1 since the suppression of cyclin D2 levels by shRNA compared to cyclin D2 blocked the increased tumor growth induced by L1 (L1+shcyclin D2 cl1, and cl2, compared to L1 cl2)." (PMID 39513917, 2024). "Specifically, S-nitrosylation of DNMT3B reduces its enzymatic activity, leading to an abnormal upregulation of the Cyclin D2 gene (CCND2), which is necessary for the proliferation of certain tumor cells." (PMID 39185313, 2024). "XHP intervention resulted in downregulation of these tumor suppressors (CCND2, PRKCG, CCN4) in tumor tissues and PC-3, DU145 cell lines, revealing XHP's regulatory role in the Wnt pathway." (PMID 38994113, 2024). "FBXL8 was found to interact with two tumour suppressors, cyclin D2 (CCND2) and interferon regulatory factor 5 (IRF5)." (PMID 36855778, 2023). "In tumor tissues, seven gene amplification mutations included CDK4 (Mutation abundance, MA:1.57), AKT2 (MA:1.65), CCND2 (MA:1.63), MDM2 (MA:1.57), NTRK1 (MA:2.38), AXL (MA:1.65), and KRAS (MA:1.63), as well as the AFF3 gene missense (c.1781_1787del insC)." (PMID 37089080, 2023). "Upon exposure to molecules 25 and 27, and particularly to molecule 25, an increased cyclin D2 immunoreactivity was observed, indicating that the anti-tumor activity of these drugs involves cell cycle inhibition." (PMID 37568789, 2023). "MiR-155 is another miR known to be a tumour-promoting factor in many cancers by regulating the BCL6/cyclin D2 axis." (PMID 37242569, 2023). "These genes include Cyclin D2 (Ccnd2), which is required for neoplastic cell proliferation in some tumor types." (PMID 36739439, 2023). "In particular, analysis of the hedgehog (HH) targets Gli1, MycN and Cyclin D2 proteins confirmed a similar SHH activity in the tumour samples of both backgrounds." (PMID 35839783, 2022). "The specific targeting of mRNAs encoding for the cell cycle regulators cyclin D2 (CCND2) and cyclin E2 (CCNE2) by expression of adeno-associated virus mediated by miR-26a resulted in considerable tumor reduction in a mouse model of HCC." (PMID 36071981, 2022). "While the comparison of expression data between tumor and normal samples showed that 8 out of 36 ARGs were significantly differentially expressed, including CCND2, CXCL6, KCNJ8, LPL, SERPINA5, SLCO2A1, VTN, and APOH." (PMID 35836112, 2022). "In the gene‐specific tumor promoter methylation analysis, higher levels of MPB and PPB, and the multiple parabens were associated with higher odds of hypomethylated CCND2 promoter‐defined BC compared to controls." (PMID 35975911, 2022). "To confirm the pattern of CCND2 in tumor tissues, we further analyzed CCND2 levels in tumor tissues by both western blot and IHC assay." (PMID 35306579, 2022). "IHC result clear also shows CCND2 level in tumor tissues (n = 12) are higher than non-tumor ovary tissues (n = 15)." (PMID 35306579, 2022). "The results showed that the expression of CCND2 was notably higher in tumor tissues than in adjacent normal tissues." (PMID 35033075, 2022).